IL1B (interleukin 1 beta)
Diseases named in the same sentence as IL1B in open-access papers (continued):
Sharing a sentence is not in itself a finding about the gene and the disease.
autoimmune disease (continued). "We have a long-standing interest in the adjuvant effect of lipopolysaccharide (LPS) on the development of autoimmune disease, but only recently has LPS been shown to mediate its effects in part by increasing TNF-α, IL-1β, and IL-18 levels through TLR4 signaling." (PMID 15550215, 2004). "Also, miR-23b (from the same cluster) has been shown to regulate the expression of μ-opioid receptors and to be underexpressed in various autoimmune diseases via suppressing interleukin 17 (IL-17), tumor necrosis factor α (TNF- α), or IL-1β-induced NF-kB activation." (PMID 39273498, 2024). "Additionally, unlike IL-1β, IL-1α is absent in the systematic circulation, indicating that the involvement of IL-1α in autoimmune diseases is limited to local tissues rather than systematic." (PMID 39062908, 2024). "In autoimmune diseases, it was found TCRαβ+ DNT cells might arise from CD8+ T cells and displayed a distinct cytokine production profile by producing proinflammatory mediators that include IL-1β, IL-17, IFN-γ, CXCL3, and CXCL2." (PMID 36443691, 2022). "Protective immunity is supported by IL-1β but, if not controlled, this highly inflammatory cytokine may contribute to autoinflammatory and autoimmune diseases." (PMID 28645296, 2017). "But importantly, IL-1β and IL-6, both found to be increased in VERA patients, are known to promote the differentiation of Th17 cells, which in turn secrete IL-17A and IL-22, two cytokines that were elevated in VERA patients and have an essential function in the pathogenesis of autoimmune diseases." (PMID 20961415, 2010). "Considering that these results hinted that IL-1β production may be indicative of the host inflammatory condition, when compared to patients with other diseases (especially autoimmune diseases), it is reasonable to expect that plasma IL-1β levels would be also higher in non-TB patients." (PMID 26881918, 2016). "Interestingly, in models of autoimmune diseases, such as EAE and collagen-induced arthritis (CIA), the induction of the Th17 cells require the presence of a mixture of killed Mycobacterium tuberculosis, that has been recently discovered to induce, via dectin-1 and TLR4, the release of IL-1β." (PMID 23874332, 2013). "Elevated IL-8, IL-10, IL-1β, and TNF-α levels have been reported in subclinical hypothyroid HT patients, though this study did not assess concurrent autoimmune diseases or the potential adverse metabolic impact of hypothyroidism." (PMID 39518417, 2024). "In the absence of IL-6 or IL-1β, the TGF-β signaling pathway induces the differentiation of regulatory T cells, which prevent autoimmune diseases by inducing anti-inflammatory cytokines." (PMID 33126239, 2020). "Moreover, IRF2 silencing significantly attenuated canonical and noncanonical inflammasome-mediated pyroptosis and IL-1β release, suggesting that IRF2 is a reliable drug target for the treatment of autoimmune disease." (PMID 35693810, 2022).
ischemia (256 papers, 2006 to 2026). A hypoperfusion of the BLOOD through an organ or tissue caused by a PATHOLOGIC CONSTRICTION or obstruction of its BLOOD VESSELS, or an absence of BLOOD CIRCULATION. "Macrophages play a central role by forming foam cells and secreting pro-atherogenic cytokines, such as TNF-α, IFN-γ, and IL-1β, which destabilize atherosclerotic plaques, expanding the lipid core and increasing the risk of thrombosis and ischemia." (PMID 40243563, 2025). "IL-1β: IL-1β contributes to retinal endothelial cell apoptosis, microglial activation, and pericyte loss, exacerbating ischemia." (PMID 40722794, 2025). "By inhibiting inflammasome complex formation, colchicine decreases IL-1β production, potentially reducing inflammation and tissue damage associated with ischemia." (PMID 40149903, 2025). "Activation of microglia and astrocytes caused by ischemia leads to production of pro-inflammatory cytokines (IL-6, IL-1β, and TNF-α), and the release of chemotactic factors, which further increase the permeability of BBB." (PMID 38364236, 2024). "It has been shown that IL-1β is important in the neurotoxicity of LPS and secondary brain injury caused by neuroinflammation during traumatic brain injury and ischemia." (PMID 32041252, 2020). "ASC-deficiency in a partial liver ischemia showed an inhibition in the caspase 1/IL-1β signaling and protection against liver IRI." (PMID 33114395, 2020). "In conclusion, flurbiprofen axetil preconditioning improves neurological function and neuronal survival after ischemia, which is associated with inhibition of IL-1β, TNF-α, and TXB2 synthesis, creating a favorable TXB2/6-keto-PGF1α ratio in rats." (PMID 29540536, 2018). "Accumulating evidence has shown that inflammation plays an important role in modulating cerebral injury and apoptosis caused by ischemia/reperfusion; we thus examined the effects of ischemic postconditioning on the production of neurotoxic cytokine IL-1β." (PMID 24460643, 2014). "Left lung ischemia-reperfusion was associated with reduced levels of both IL1β (p < 0.001) and IL6 (p < 0.001) in the right lung." (PMID 24146959, 2013). "Proinflammatory cytokines, such as tissue necrosis factor-α (TNF-α), interleukin (IL)-1β, and IL-6 have been implicated as important mediators of ischemia/reperfusion injury following both focal and global cerebral ischemia." (PMID 23056034, 2012). "Reduced levels of IL-1β in the rat brain’s cortex improve neurological impairment by decreasing the infarct size and blocking neutrophil infiltration into injured tissue caused by ischemia." (PMID 36793730, 2023). "In our animal study, the mRNA level of IL-6, TNFα, and IL-1β was increased 24 h after ischemia induction; this was associated with the presence of M1-like macrophages and the expansion of cerebral infarction although the mRNA level of IL-6 was low during the first 3 h." (PMID 29110250, 2018). "When recombinant IL-1β was injected into the lateral ventricles or directly into the brain parenchyma in the animal models, the levels of IL-1α and IL-1β significantly increased, which would result in ischemia or other causes of brain damage." (PMID 24063019, 2013). "Interestingly, we have shown that dietary potassium supplementation in SHRSP causes a dramatic reduction in the plasma concentration of IL-1β, presenting the possibility that this too has an effect on the outcome of ischemia in the normotensive rat." (PMID 18237391, 2008). "Within 24 h of the onset of ischemia, brain tissues exhibit a substantial inflammatory response, accompanied by a significant escalation in pro-inflammatory cytokine levels, such as IL-1β and TNF-α, which further exacerbate brain injury." (PMID 40260076, 2025). "In the ischemia group, the mRNA expression of the IL-1β gene increased compared to the control group (P<0.01)." (PMID 40809171, 2025).
ischemia (continued). "Although no studies directly link duraplasty to microglial phenotype shifts, surgical decompression improves spinal cord perfusion, reducing ischemia and secondary injury signals (e.g., ROS, IL-1β) that drive microglial activation." (PMID 40278428, 2025). "Especially, the pro-inflammatory phenotype of microglia induced by ischemia and LPS is characterized by increasing productions of iNOS, IL-1β, IL-6, TNF-α, reactive oxygen species (ROS) and NO resulted in the dysfunction of the CNS." (PMID 40289983, 2025). "CD4+ and Gene expression of IL-1β were significantly increased in the Ischemia group compared to the control group." (PMID 40809171, 2025). "Microglia, the primary mediators of neuroinflammatory processes in the CNS, respond to various pathological changes, including injury, ischemia, and infection, by expressing a range of cytokines like IL-1β, IL-6 and TNFα." (PMID 38600587, 2024). "Previous research has shown Melittin’s anti-inflammatory actions in cases of cerebral ischemia, where it reduced the elevated cytokine levels (IL-1β, IL-6, TNF-α) post-ischemia by inhibiting the NF-κB signaling pathway linked to inflammatory factor production." (PMID 38732255, 2024). "Nesfatin-1 reduced microglia proinflammatory activation by decreasing IL-1β, IL-6, and TNFα expression in a rat ischemia model." (PMID 39295865, 2024). "In pathological conditions, increased pro-inflammatory cytokines such as IL-1β, IL6, and TNFα cause brain damage due to ischemia associated with BBB disruption." (PMID 39204239, 2024). "Inhibiting CX3CR1 with siRNA exacerbates ischemia‐induced microglial activation, enhances IL‐1β expression, and worsens ischemia‐induced cognitive impairment." (PMID 39691417, 2024). "Administration of Captopril, Losartan, or their combination resulted in a significant (p < 0.01) decrease in TNF-α, IL-1β, and IL-6 levels which was increased at the beginning by ischemia compared to untreated controls." (PMID 37259385, 2023). "Trolox has been shown to have a neuroprotective effect against ischemia and IL-1β-mediated neurodegeneration." (PMID 37373089, 2023). "Here we show that the complement peptide C3a exerts differential effects on the expression of Gfap, C3, Nes, Tnf and Il1b in naïve astrocytes, astrocytes after ischemia and astrocytes exposed to LPS." (PMID 36097103, 2023). "Potent immune regulators such as IL‐1β are mediated by inflammasomes and often induced by pro‐inflammatory monocytes following ischemia." (PMID 37849042, 2023). "Another study highlighted that the level of IL-1β was remarkably increased in the injured kidney tissues following half an hour of ischemia and two hours of reperfusion in a rat model." (PMID 38024816, 2023). "By acting as an inflammatory mediator, IL-1β is injected before estrogen is delivered to the body to precipitate the death of ischemia cells." (PMID 36793730, 2023). "Although the expression of caspase-1/11 and IL-1β/IL-18 is controversial due to the differences in subjects and the time of ischemia, consistent with our study, the expression of GSDMD and GSDMD-N increased during myocardial ischemia." (PMID 35783187, 2022). "The release of inflammatory factors (e.g., TNF-α, IL-6, and IL-1β) after ischemia-induced macrophage activation is responsible for IR damage and for exacerbating liver microcirculation disorders." (PMID 35966821, 2022). "The anti-inflammatory effects of Tat-CHIP were assessed in the hippocampus 6 h after ischemia induction by measuring pro-inflammatory cytokine levels, such as IL-1β, IL-6, and TNF-α." (PMID 36450819, 2022). "Direct reduction of IL1β levels or blocking of the downstream signal of IL1β contribute to helpful cardiac remodeling and improvements of HF phenotype induced by ischemia/infarction, pressure overload, or anthracycline toxicity." (PMID 35647084, 2022). "The Interleukin 1 beta highlighted in the angiogenesis pathway was previously demonstrated in high levels acutely in rats with focal ischemia." (PMID 35777300, 2022).
ischemia (continued). "During ischemia, cytokines, such as IL-1β, IL-6 and TNF-α are produced by a variety of activated cell types, including microglia and neurons (Huang, Upadhyay & Tamargo, 2006)." (PMID 34123580, 2021). "AP39 also exerted prominent anti-inflammatory activity in reducing the release of Il-1β, Il-6 and TNFα in brain areas particularly affected by ischemia." (PMID 34360581, 2021). "In the Tat peptide- and Control-SH3GL2-treated groups, TNF-α, IL-1β, and IL-6 levels were significantly increased in the hippocampus 6 h after ischemia compared to those in the control group." (PMID 33572372, 2021). "In summary, the pretreatment with GPE-R significantly promotes the survival of neurons in the hippocampal CA1 region after ischemia/reperfusion by reducing reactive microglia and pro-inflammatory cytokines such as IL-6, IL-1β, and TNF-α." (PMID 33435613, 2021). "TNF-α, IL-1β, and IL-6 are the major pro-inflammatory cytokines that aggravate the inflammatory response after ischemia injury." (PMID 34238326, 2021). "The mechanism research showed that the levels of NLRP3, caspase-1, IL-1β and IL-18 were all increased in rat brain with I/R injury, which was ischemia for 1 h and then reperfusion for 24 h." (PMID 34445481, 2021). "As a result of ischemia, astrocytes release vimentin, nestin, IL-1β, monocyte chemotactic protein-1, and glial fibrillary acidic protein, which contribute to the development of reactive gliosis and the formation of glial scars after ischemia." (PMID 33922467, 2021). "Hydrogen gas inhalation has been proven to decrease the levels of inflammatory cytokines, including TNF-α, IL-1β, and IL-6, in ischemia/reperfusion injury or the retina, liver, and brain." (PMID 34769482, 2021). "Another study conducted in the rat model of cerebral ischemia has shown that rosiglitazone decreased ischemia-induced levels of TNF-α, IL-1β and IL-6 and it induced ischemia-downregulated IL-10 level." (PMID 34830207, 2021). "The data suggested that sRAGE suppressed the transcription of IL-1β and IL-18 in primary cultured cardiomyocytes following ischemia-reperfusion injury." (PMID 34912499, 2021). "Several reports suggested that under the effect of insult, such as ischemia or substance abuse, the brain endothelium begin to release proinflammatory cytokines, particularly IL-1β." (PMID 33648543, 2021). "So, we used immunohistochemistry to detect NLRP3, Caspase-1 and IL-1β levels in the right striatum of ischemia region." (PMID 33461169, 2021). "Meanwhile, OA significantly decreased the ischemia-induced increase in pro-inflammatory cytokine IL-1β." (PMID 34413777, 2021). "Many stimuli such as ischemia and chronic inflammation increase the IL-1β expression levels in CNS systems." (PMID 32992470, 2020). "This led to a greater increase in TLR4, P2X7, IκBα activation, NLRP3, ASC, cleaved caspase-1, and pro-inflammatory cytokine IL-1β levels in the Stress+ISCH group compared to the ischemia-alone group." (PMID 32466385, 2020). "Application of HYP9 in vivo alleviated the brain infarct lesion, astrocytes population, apoptosis, and interleukin-6 (IL-6) and IL-1β release in mouse cortices after ischemia." (PMID 33604333, 2020). "In initial studies we analyzed inflammatory responses induced by local injections of leukotriene B4 (LTB4) and IL-1β and by a local pathophysiological insult of ischemia/reperfusion (IR) injury (all within 2 to 4 hours)." (PMID 31971917, 2020). "It is demonstrated that the increase of some cytokines including IL-6, IL-1β, and TNF-α in ischemia models are associated with pathways that participate in apoptotic neuronal death." (PMID 32963745, 2020). "TRPV1, which is activated after ischemia intensely mediate astrocyte activation compared to microglia, increases IL-1β release and exacerbates ischemia-induced brain damage (brain atrophy, infarct size, and neurobehavioral loss)." (PMID 31142341, 2019).
ischemia (continued). "Consistently, we found that ischemia-induced TREM-1 promoted IL-1β, IL-18, IL-6, CXCL-2, MCP-1, and CXCL-1 productions in microglia as well as the expression of MPO and ICAM-1 following ischemic injury." (PMID 31324751, 2019). "Many preclinical studies have focused on modifying IL-1β levels by exogenous administration of recombinant IL-1β or selective anti-IL-1β neutralizing antibodies on experimental ischemia in rodent models." (PMID 31727174, 2019). "Astrocytes activated by ischemia and anoxia secrete many pro- and anti-inflammatory factors, such as IL-1β, IL-6, TNF-α, TGF-β, VEGF-A, MCP-1 CXCL-1, MMP-2, and MMP-9, which influence BBB integrity." (PMID 31779652, 2019). "There was significant reduction by HDACi of IL-1β following ischemia (SMD −2.27, 95% CI −3.63 to −0.91) and trauma (SMD −8.44, 95% CI −12.35 to −4.54) but not with other injury types." (PMID 30528323, 2019). "A growing body of evidences also suggests that MEK/ERK pathways are responsible for the elevated level of TNF-α, IL-1β, IL-6, and iNOS following ischemia, which further highlights their neuroinflammatory role." (PMID 31049133, 2019). "Electroacupuncture is also reported as a safe and effective therapy to attenuate the overactivation of Iba-1 and ED1 positive microglia and the expression of TNF-α, IL-1β, and IL-6 and leads to reduced neurological and sensorimotor impairment in ischemia." (PMID 31031649, 2019). "In the ND 2-min TI group, the IL-1β level was significantly increased (about 1.6-fold, p < 0.05, and 1.7-fold, p < 0.05 of the ND sham group, respectively) at 2 and 5 days post-ischemia." (PMID 31546722, 2019). "Reperfusion injury after ischemia is characterized by a severe immune response, including elevated reactive oxygen species and an increase in pro-inflammatory cytokines, including IL-1β, IL-6 and TNF-α." (PMID 31513644, 2019). "For instance, brain slice studies have shown that ischemia, which upregulates the expression of cytokines such as IL-1β and TNF-α, induces Cx43 dephosphorylation." (PMID 29587860, 2018). "By 14 days post-ischemia, TNFα and IL-1β levels tended to come back down, whereas the expression of IGF-1 were increased, similar to our astrocyte-activated microglial cultures." (PMID 29764475, 2018). "More recently, we have shown that systemically infused anti-IL-1β mAb also decreases the transport of the IL-1β cytokine protein across the BBB after ischemia, at least in part by complexing with free IL-1β in the systemic circulation in fetal sheep." (PMID 29875342, 2018). "IgG leakage, tight junction protein loss, and inflammatory cytokines IL-1β, IL-6, and TNF-α reduced in mesenchymal stem cell-treated mice compared to the control group following ischemia (p < 0.05)." (PMID 29724240, 2018). "Previous studies have shown that COX inhibitors are able to suppress TNF-α, IL-6, and IL-1β in renal tissue after ischemia." (PMID 29535870, 2018). "The infusions of the neutralizing anti-IL-1β mAb after ischemia reduced the I/R related increases of IL-1β proteins within the brain parenchyma." (PMID 29875342, 2018). "Initial elevations are detected at 1–3 h after ischemia onset and, like IL-1β, have a biphasic pattern of expression with a second peak at 24–36 h." (PMID 29540536, 2018). "In the present study, both pre- and post-ischemia melatonin administrations were able to decrease IL-1β levels in both hemispheres in a significant manner (p < 0.01)." (PMID 30029514, 2018). "Administration of the H4R antagonist, JNJ, reduced TNF-α and IL-1β assayed in the peripheral plasma 7 days after ischemia." (PMID 30420807, 2018). "The ischemia vehicle group showed a higher level of IL-1β compared to the sham control group (data not shown, p < 0.01), as evidenced by the increased number of IL-1β+/Ly6C+ cells in the infarct area." (PMID 30405724, 2018).